MUC5AC (mucin 5AC, oligomeric mucus/gel-forming)
Diseases named in the same sentence as MUC5AC in open-access papers (continued):
Sharing a sentence is not in itself a finding about the gene and the disease.
cancer (continued). "Other research, comparing different subtypes of CCs, confirmed that the most abundantly represented mucins in these cancers were MUC1 (~66%) and MUC5AC (~61%), followed by MUC2 (~24%) and MUC6 (~14%)." (PMID 30875782, 2019). "The expression rates in cancer lesions (more than 5% of carcinoma cells stained) were MUC1, 51.7% (31/60); MUC2, 26.7% (16/60); MUC3, 55% (33/60); MUC4, 51.7% (31/60); MUC5AC, 33.3% (20/60); MUC6, 10% (6/60) and MUC16, 8.3% (5/60)." (PMID 24722639, 2014). "Mucin 5AC (MUC5AC) is secreted by goblet cells of the respiratory tract and, surprisingly, also expressed de novo in mucus secreting cancer lines." (PMID 23741618, 2013). "By combining measurements of the standard CA 19-9 assay with detection of CA 19-9 on MUC5AC and MUC16, the sensitivity of cancer detection was improved relative to CA 19-9 alone in each sample set, achieving 67–80% sensitivity at 98% specificity." (PMID 22220206, 2011). "MUC5AC and MUC6 expression were frequently observed in early carcinoma (>50%) than advanced carcinomas (>25%)." (PMID 16545139, 2006). "Although these proteins are frequently co-expressed and act cooperatively in normal tissues, the relationship between the expression of TFF1 and MUC5AC was rather weak in cancer, since only 7% of 2289 cancer samples with TFF1 and/or MUC5AC expression expressed both proteins." (PMID 39410561, 2024). "Therefore, we investigated the clinical significance of MUC1, MUC2, MUC5AC, and MUC6 expression in AoV cancer." (PMID 38893239, 2024). "Similarly, in the same cancer, CD44 was targeted through the direct administration of ON-TARGET plus human CD44 siRNA or indirectly by silencing mucin (MUC5AC) gene expression using a small hairpin RNA construct (pSUPER-Retro-shMUC5AC)." (PMID 38672650, 2024). "Therefore, we treated cancer cells with the CCL2 ligand (100–300 ng/ml) for 24–48 h and found that MUC5AC expression was increased in A549-BrM cells in a dose-dependent manner." (PMID 38825648, 2024). "Poorly differentiated (G3) carcinomas tended to show a loss of CDX2 (27/33 cases) but not of MUC2 and MUC5AC." (PMID 37240039, 2023). "On our TMA, 476 of 599 (79.5%) arrayed cancers were analyzable for MUC5AC IHC.Reasons for non-informative cases (n = 123, 20.5%) includedlack of tissue samples or absence of unequivocal cancer tissue in the TMAspot." (PMID 35764407, 2022). "The occurrence of relevant subgroups of MUC5AC positive and negative tumors within many clinically relevant cancer types raises, however, the question of a possible prognostic or predictive role of MUC5AC expression." (PMID 34547930, 2021). "It is of note that—irrespective of a cancer origin—patterns of MUC5AC expression often contain a limited number of strongly positive cells being interspersed between negative cancer cells in a fairly regular way (mosaic pattern)." (PMID 34547930, 2021). "Of these cases, 1220 cancers were analyzable for both MMR and MUC5AC." (PMID 33373033, 2021). "Furthermore, the cancer cells exhibited strong expression of “intestinal” differentiation markers, including CDX2, MUC2, and MUC5AC." (PMID 34487254, 2021). "dMMR was found in 21.3% of 169 cancers with MUC5AC positivity but in only 4.6% of 1051 cancers without detectable MUC5AC expression (p < 0.0001)." (PMID 33373033, 2021). "The fact that MUC5AC expression was also unrelated to aggressive cancer phenotype in our 1051 pMMR cancers demonstrates that adverse prognostic effects of MUC5AC are not obscured by the favorable prognostic influence of dMMR." (PMID 33373033, 2021). "In addition, CrD-SBC patients with co-expression of MUC5AC and CK7 by the cancer (15 cases) featured a worse prognosis in comparison with those negative for both markers (17 cases) or with expression of either MUC5AC or CK7 (20 cases)." (PMID 33963925, 2021).
cancer (continued). "It is noteworthy that HIF1α and BMP4 have both been reported not only to promote MUC5AC expression, but also to upregulate expression of OCT4, which is a pluripotency gene and a marker for lung and cancer stem cells." (PMID 33015064, 2020). "However, we did not observe down-regulation of other stem cell markers (CD133 and Lgr5), suggesting that both MUC5AC and CD44 have a positive role in maintaining a specific subset of the cancer stem cell population." (PMID 32098629, 2020). "Conversely, in the 30 human cancer cell lines and various normal tissues, expression patterns of MUC5AC and Gli did not coincide wholly: MUC5AC showed cell line-specific or tissue-specific expression whereas Gli mostly revealed ubiquitous expression." (PMID 25166306, 2014). "In this study, we investigated the relationships between mucin expression and clinicopathologic factors in 60 SBC cases, in which expression profiles of MUC1, MUC2, MUC3, MUC4, MUC5AC, MUC6 and MUC16 in cancer and normal tissues were examined by immunohistochemistry." (PMID 24722639, 2014). "MUC5AC and MUC6 expressions were decreased in advanced carcinomas (>25%)." (PMID 16545139, 2006). "However, there were no significant changes in cancer cell proliferation when MUC5AC was knocked down, and the cells were cocultured with astrocytes." (PMID 38825648, 2024). "Mucin core protein (MUC) in the cancer cells was negative for MUC5AC, MUC6, and MUC2." (PMID 37234391, 2023). "It should be noted that PDAC is not the only cancer with overexpression of MUC5AC." (PMID 37241027, 2023). "Moreover, claudin-18 (≥1%) was positively associated with cytokeratin 7 (CK7) and MUC5AC expression, showing CK7+/MUC5AC+ carcinomas the highest rate of positive cases, whereas a negative correlation was found between claudin-18 and CDX2 expression." (PMID 35925388, 2022). "Among 132 cases of PDAC, 92% were positive for MUC5AC,60MUC5AC mRNA expression was also higher in tumoral tissues compared with para‐tumoral tissue, which might be correlated with PDAC invasion, suggesting its role in the acceleration of cancer progression." (PMID 32745356, 2020). "However, MUC5AC often showed co-expression of MUC2, indicating that the cancer still has goblet cell lineage, and its gastric differentiation may simply be superficial." (PMID 29786668, 2018). "However, a subset of cancer patients with no elevation in the standard CA 19-9 assay showed elevations of the CA 19-9 antigen specifically on the proteins MUC5AC or MUC16 in all sample sets." (PMID 22220206, 2011). "Furthermore, after 3 months the engrafted cells do not express the cancer-specific mucin, MUC5AC." (PMID 32098630, 2020). "On the other hands, we found that PCI-64 cells by which MUC5AC was not originally expressed showed no augmentation of MMP-3, α3-integrin or VEGF, indicating that MUC5AC might not play a central role in progression of cancer like PCI-64 cells which have low level expression of MUC5AC." (PMID 20492722, 2010). "Akin to MUC5AC, MUC6 expression decreased with cancer formation in the esophagus but not in the stomach." (PMID 36994101, 2023). "By determining expressions of the three MUCs in additional 68 pairs of samples, we confirmed the upregulations of MUC5AC and MUC5B but not MUC3A in cancer tissues." (PMID 37324942, 2023). "Not surprisingly, similarity among different cancer types was identified in only 6 out of 23 clusters, including E3 (IRS2, KRT6A), E5 (CD24, STMN1), E8 (GKN1, MUC5AC), E9 (PHGR1, TFF3), E10 (TFF3, TPO) and E13 (VTN and ITIH5)." (PMID 36333338, 2022). "Both, poorly cohesive and non-poorly cohesive cancers with ≥ 10% SRCs, were more frequently MUC2, MUC5AC, or ABPAS positive compared to cancers with < 10% SRCs." (PMID 32488651, 2020). "In our present case, Brunner’s gland adenocarcinoma was indicated by the fact that the cancer was surrounded by Brunner’s gland hyperplasia and immunostaining analysis was positive for MUC6 and negative for MUC5AC." (PMID 31728658, 2019).
cancer (continued). "In Case 1, the dysplastic and carcinoma cells were strongly positive for CK7, MUC1, and MUC6 but negative or only focally positive for CK20, MUC2, CDX2, and MUC5AC." (PMID 27656307, 2016). "However, the carcinoma cells were immunopositive for estrogen and progesterone receptors and GATA3 and negative for CDX2, Hep Par 1, and MUC5AC." (PMID 25400965, 2014).
adenocarcinoma (38 papers, 2004 to 2025). A common cancer characterized by the presence of malignant glandular cells. "In histological studies of the colorectal adenocarcinoma differentiation, the MUC2 level was found to decrease, and MUC5AC tends to increase when CRC progresses from moderately to poorly differentiated adenocarcinoma." (PMID 40699805, 2025). "The other adenocarcinoma consisted of MUC5AC-positive atypical cells growing in a glandular pattern." (PMID 40463821, 2025). "The first endoscopic biopsy, due to the limited tissue sample, showed immunohistochemistry results of CKpan (+), CK7(+), MUC5AC (focal+), and Ki-67(partly+), favoring a diagnosis of adenocarcinoma." (PMID 41333217, 2025). "MUC5AC staining was notably stronger in the adenocarcinoma brain metastasis tissues than in the primary lung tumor tissues." (PMID 38825648, 2024). "MUC5AC‐positive adenocarcinoma frequently developed in the gastric location (p = 0.041) and tended to demonstrate poorly differentiated (p = 0.023) and lymphovascular invasion tumors (p = 0.013)." (PMID 37602699, 2023). "Intestinal-type adenocarcinomas generally express CDX-2, MUC2 and CD10, whereas the gastric-type adenocarcinomas express MUC5AC and MUC6." (PMID 35565398, 2022). "Panels of immunohistochemistry including MUC1, MUC2, CDX2, CK20 and MUC5AC can help in the classification of adenocarcinomas as intestinal or pancreatobiliary type in a substantial proportion of cases." (PMID 35565398, 2022). "Next, we examined MUC5AC expression in colon TMA, which showed a higher expression of secretory mucin MUC5AC protein in both adenocarcinoma (n = 34, p < 0.01) and metastatic adenocarcinoma (n = 20, p < 0.01) patient tissues." (PMID 32098629, 2020). "Based on this background information, this study investigated the pattern of expression of MUC2 and MUC5AC mucin gene protein products using immunohistochemistry in patients with adenocarcinoma arising in BE." (PMID 19272137, 2009). "Immunohistochemistry showed MUC5AC expression denoting a gastric type Adenocarcinoma." (PMID 19272137, 2009). "MUC2 and MUC5AC levels were shown to be very high in IPMT compared to adenocarcinomas." (PMID 15494719, 2004). "Pathologic examination of these xenografts demonstrated solid, poorly differentiated adenocarcinoma, with extensive PAS, Alcian blue, and MUC5AC positivity." (PMID 38632190, 2024). "A total of four studies looked specifically at the adenocarcinoma of the oesophago-gastric junction (GOJc), analysing MUC1, MUC2, MUC5AC and MUC6 in 191 surgically resected specimens." (PMID 37958425, 2023). "Though the two cell lineages were both of an adenocarcinoma origin, we showed that the IAP and MUC5AC gene expressions are restricted, respectively, to Caco-2 cells and HT29-5M21 cells." (PMID 16670004, 2006). "Importantly, we also identified the oral taxa Porphyromonas and Megasphaera to be enriched in adenocarcinoma with low MUC1 and MUC5AC expression, respectively." (PMID 37085819, 2023). "The relation between MUC5AC expression in adenocarcinoma and adjacent mucosa was not statistically significant." (PMID 37240002, 2023). "MUC5AC-positive non-tumoral mucosa was adjacent to negative adenocarcinoma in more than 60% (16/27), and MUC5AC-negative mucosa was adjacent to positive or negative adenocarcinoma in the same proportion (50%, 4/8)." (PMID 37240002, 2023). "Interleukin-9, which induces MUC-2 and MUC-5AC gene expression in the lung, and its receptor, IL-9Rα, were expressed at variable levels in all cases of PMP with increased IL-9 expression in the epithelial PMP cells compared with adenocarcinoma." (PMID 17031402, 2006).
inflammation (19 papers, 2012 to 2026). Aberrant reaction of the microcirculation characterized by movement of fluid and leukocytes from the blood into extravascular tissues. "Chronic airway inflammation in βENaC-Tg mice is associated with mucus hypersecretion, as evidenced by goblet cell metaplasia and elevated expression of secreted mucins (MUC5AC and MUC5B) that were found to be reduced in βENaC-Tg mice that lack NE (βENaC-Tg/NE-/-)." (PMID 36362203, 2022). "As for Muc5ac, the revealed imbalance between mRNA and protein expression can be associated both with a slowdown of protease-dependent mucus degradation and an impairment of mucociliary clearance in acute asthmatic airway inflammation." (PMID 35625754, 2022). "For example, our observations suggest that MUC5AC directly augmented RV-induced airway inflammation." (PMID 35239513, 2022). "LYN downregulates allergen-induced airway inflammation, and its overexpression decreases mucus secretion and MUC5AC transcription in mice exposed to allergens." (PMID 35886039, 2022). "Anti-IL-17 antibody can reduce the number of neutrophils in mice and the concentration of MUC5AC in bronchoalveolar lavage fluid and attenuate neutrophilic airway inflammation." (PMID 33335558, 2020). "In the present study, we demonstrated that the transcript levels for muc1, muc2, muc3, muc4, muc5b and muc13 in lung tissue were unaltered, whereas muc5ac transcript expression was significantly increased during allergen-induced airway inflammation in mice." (PMID 28205598, 2017). "OVA-induced airway inflammation, airway mucus hyper-secretion, the up-regulation of E-selectin and MUC5AC were remarkably inhibited by GLP-1 in mice (all p < 0.01)." (PMID 26343632, 2015). "During lung inflammation, C3a/C3aR mediated signaling in lung epithelial cells induces the expression of Muc5ac." (PMID 23285141, 2012). "A finding demonstrates that neutrophil elastase can increase PAR-2 expression and MUC5AC mucin release may also implicate the involvement of PAR-2 in airway inflammation." (PMID 24876677, 2014). "S100A8, S100A9, and S100A12 were supposed to directly stimulate the production of mucin 5AC (MUC5AC), a major mucin protein in the airway which closely correlated with airway inflammation." (PMID 35348596, 2022). "Furthermore, our data also revealed that the effects of curcumin on OVA-induced airway inflammation and mucus hypersecretion in mice and IL-4-induced overexpression of MCP-1 and MUC5AC in BEAS-2B cells were largely blunted by shRNA-PPARγ." (PMID 31073274, 2019).
respiratory disease (16 papers, 2011 to 2025). "The respiratory disease associated MUC5AC mucin structure shows how it interacts with other MUC5AC to form net-like polymers." (PMID 40016425, 2025). "Background and objective: Dysregulation of respiratory mucins, MUC5AC in particular, has been implicated in respiratory disease and MUC5AC expression is up-regulated in response to environmental challenges and inflammatory mediators." (PMID 23551418, 2013). "Thus a false positive association of MUC5AC with respiratory outcomes certainly cannot be excluded, but it is noteworthy that this gene region is now repeatedly showing association with respiratory disease." (PMID 23551418, 2013). "Overproduction of the MUC5AC gene is a characteristic of many respiratory diseases including CF, asthma, and COPD, creating hyper-concentrated mucus, which is thicker, more adherent and prone to mucus plugging." (PMID 33868294, 2021). "TMEM16A expression was previously shown to be increased by bacterial components and Th2 cytokines in respiratory system diseases, and to aid the secretion of MUCs, especially MUC5AC and MUC5B39–41." (PMID 32472021, 2020). "The top ten genes (Clca1, Chil4, Itln1, Tff1, Muc5ac, Clca3b, Chodl, Pla2g4c, Mmp10, and Stac2) with the highest fold change are involved in various inflammatory responses and respiratory diseases." (PMID 33066398, 2020). "Among several mucin genes, Muc5ac is a major constituent of the mucous layer in the airways of humans with respiratory diseases and therefore serves as a marker for mucus cell hyperplasia." (PMID 26084512, 2015). "It will be important to determine the site of synthesis of Muc5ac and Muc5b in horses with airway obstruction to inform future therapeutic developments targeted at modulating mucin production in horses with respiratory disease." (PMID 21602926, 2011). "Thus, the decrease in TRPA1, TRPV1, and MUC5AC in the lungs following the administration of LM extract should improve respiratory disease symptoms, such as cough and mucus production, in mice." (PMID 39519565, 2024). "However, the activation of EGFR, also leads to goblet cell hyperplasia, mucus hypersecretion, and overproduction of MUC5AC, which may exacerbate the pathological changes in respiratory diseases." (PMID 33868294, 2021). "Therefore, reducing MUC5AC and MUC2 expression may effectively alleviate excessive mucus production in respiratory diseases." (PMID 37687271, 2023). "Type II gastric mucin contains mucin 2 and mucin 6 (MUC2/MUC6), as well MUC5AC, and although these are not the major secreted mucins in saliva, they are gel-forming and serve as a surrogate for the secretory gel-forming mucins in saliva upregulated during respiratory disease." (PMID 36146663, 2022).
bacterial infection (8 papers, 2011 to 2025). "A number of studies have found that high expression of MUC5AC is associated with a variety of inflammatory respiratory diseases, such as acute viral or bacterial infections and chronic airway inflammation." (PMID 40600698, 2025). "Having observed associations between concentrations of MUC5AC and airway inflammation, viral load, and secondary bacterial infections, we next determined whether airway mucins during exacerbations were related to clinical outcomes during exacerbation." (PMID 35239513, 2022). "MUC5AC was more sensitive to changes in expression during exacerbation and was therefore more predictably associated with viral load, inflammation, symptom severity, decrements in lung function, and secondary bacterial infections." (PMID 35239513, 2022). "Accordingly, we observed that changes in MUC5AC concentrations correlated with inflammation, viral load, secondary bacterial infections, and clinical measures of exacerbation severity." (PMID 35239513, 2022). "In addition, the goblet cells of the conjunctiva, compared to the stratified squamous cells, can respond to bacterial infection by secretion of the protective high-molecular-weight mucin MUC5AC." (PMID 38089811, 2023). "Other authors suggested that bacterial infection leads to increased MUC5AC expression in the colon." (PMID 38069066, 2023). "Among the many mucins secreted, MUC2 is the one most represented, but in the presence of parasitic or bacterial infections there also are secretions of MUC3 and MUC5AC." (PMID 36835003, 2023). "Furthermore, increased MUC5AC may contribute to secondary bacterial infections by other mechanisms." (PMID 35239513, 2022). "The relationship between bacterial infection and over expression of MUC2 and MUC5AC were emphasized especially in the respiratory tract and middle ear epithelial cells." (PMID 22073249, 2011). "Although, we and others showed the relationship between bacterial infection and overexpression of MUC2 and MUC5AC in the intestine, respiratory tract and middle ear infection but the transcription factor involved in the mucin gene induction was not determined during S. dysenteriae infection." (PMID 25365201, 2014).